APOC2 (apolipoprotein C2)
Description:
Component of chylomicrons, very low-density lipoproteins (VLDL), low-density lipoproteins (LDL), and high-density lipoproteins (HDL) in plasma. Plays an important role in lipoprotein metabolism as an activator of lipoprotein lipase. Both proapolipoprotein C-II and apolipoprotein C-II can activate lipoprotein lipase. In normolipidemic individuals, it is mainly distributed in the HDL, whereas in hypertriglyceridemic individuals, predominantly found in the VLDL and LDL.
Synonyms: Apo-CII; ApoC-II
Tractability: Antibody: UniProt places it where antibodies can reach, with high confidence; its Gene Ontology location is reachable by antibodies, with high confidence; UniProt predicts a signal peptide or a membrane-spanning region. PROTAC: ubiquitination databases record sites on it.
Gene: Protein-coding gene on chromosome 19 (44,945,709 to 44,949,580, forward strand). Ensembl gene ENSG00000234906.
Subcellular location: Secreted
Pathways (Reactome):
Transport of small molecules: Assembly of active LPL and LIPC lipase complexes; Chylomicron assembly; Chylomicron remodeling; HDL remodeling
Sensory Perception: Retinoid metabolism and transport
Signal Transduction: NR1H3 & NR1H2 regulate gene expression linked to cholesterol transport and efflux
Gene Ontology:
Molecular function: lipase inhibitor activity; lipid binding; lipoprotein lipase activator activity; molecular function activator activity; phospholipase activator activity; phospholipase binding; protein binding; enzyme activator activity
Biological process: cholesterol efflux; chylomicron remnant clearance; chylomicron remodeling; high-density lipoprotein particle clearance; negative regulation of cholesterol transport; negative regulation of lipid metabolic process; negative regulation of receptor-mediated endocytosis; negative regulation of very-low-density lipoprotein particle clearance; phospholipid efflux; positive regulation of fatty acid biosynthetic process; positive regulation of phospholipid catabolic process; positive regulation of triglyceride catabolic process; positive regulation of very-low-density lipoprotein particle remodeling; triglyceride homeostasis; cholesterol homeostasis; lipoprotein catabolic process; reverse cholesterol transport; triglyceride-rich lipoprotein particle remodeling; very-low-density lipoprotein particle remodeling; lipid metabolic process; lipid transport
Cellular component: chylomicron; extracellular region; intermediate-density lipoprotein particle; low-density lipoprotein particle; spherical high-density lipoprotein particle; very-low-density lipoprotein particle; early endosome
Genetic constraint (gnomAD): Loss-of-function variants: 6 observed, 11.23 expected, observed/expected ratio (o/e) 0.53, 90% interval 0.29 to 1.05. The upper end of that interval is the gene's LOEUF score, 1.05, which puts it in group 4 of 6, group 1 being the genes least tolerant of losing a copy. Missense variants: 110 observed, 123.65 expected, observed/expected ratio (o/e) 0.89, 90% interval 0.76 to 1.04. Synonymous variants: 56 observed, 51.56 expected, observed/expected ratio (o/e) 1.09, 90% interval 0.88 to 1.36.
Homologues: Orthologues: macaque APOC2 (76% identical), dog APOC2 (64% identical), rat Apoc2 (63% identical), guinea pig APOC2 (59% identical), mouse Apoc2 (59% identical), zebrafish apoc2 (25% identical).
Diseases named in the same sentence as APOC2 in open-access papers:
APOC2 is named in the same sentence as 126 diseases in open-access papers, as found by Europe PMC text mining. Sharing a sentence is not in itself a finding about the gene and the disease. The quoted sentences say what the papers report.
hypertriglyceridemia (72 papers, 2009 to 2026). A laboratory test result indicating elevated triglyceride concentration in the blood. "Overexpression of the human APOC2 gene has been associated with marked hypertriglyceridaemia, primarily due to the accumulation of large, TG-rich VLDL particles, suggesting a lipolytic defect." (PMID 41374009, 2025). "ApoC2 is an activator for LPL activity, and decreased apoC2 activities are inversely associated with hypertriglyceridemia in humans." (PMID 39234305, 2024). "In accordance with the clinical phenotype observed in human patients with APOC2 deficiency, zebrafish mutants deficient in Apoc2 exhibit hypertriglyceridemia when fed a standard diet." (PMID 37891921, 2023). "APOC2 deficiency in humans displays decreased levels of cholesterol ester, chylomicronemia, and severe hypertriglyceridemia, which is a considerable risk factor for the development of cardiovascular." (PMID 36011378, 2022). "Recently, APOC2 mimetic peptides have been developed for treatment of hypertriglyceridemia, especially in APOC2-deficient patients." (PMID 32849290, 2020). "The gene APOC2 mutation can result in hypertriglyceridemia, which is one of the main characteristics of obese subjects." (PMID 29132311, 2017). "In this study, we described a Chinese female with severe hypertriglyceridemia caused by a novel homozygous mutation in the APOC2 gene." (PMID 26772541, 2016). "Here we describe a novel homozygous mutation of the APOC2 gene, leading to truncation and loss of the entire C-terminal, in a Chinese female patient with severe hypertriglyceridemia and recurrent episodes of pancreatitis." (PMID 26772541, 2016). "Human patients with APOC2 deficiency display severe hypertriglyceridemia while consuming a normal diet, often manifesting xanthomas, lipemia retinalis and pancreatitis." (PMID 26044956, 2015). "The authors report that Apoc2 loss-of-function mutant zebrafish display chylomicronemia (build-up of chylomicrons in the blood) and severe hypertriglyceridemia, characteristics that closely resemble those seen in human patients with APOC2 deficiency." (PMID 26044956, 2015). "One important clinical complication of hypertriglyceridemia in patients with LPL or APOC2 deficiency is recurrent pancreatitis, but the underlying mechanisms are poorly defined." (PMID 26044956, 2015). "Highlighted Article: Apoc2 loss-of-function zebrafish display severe hypertriglyceridemia, which is characteristic of human patients with defective lipoprotein lipase activity." (PMID 26044956, 2015). "Patients with APOC2 or LPL deficiency show severe hypertriglyceridemia and chylomicronemia, and often manifest eruptive xanthomas, lipemia retinalis and acute and recurrent pancreatitis, which can be lethal." (PMID 26044956, 2015). "Patients with a genetic deficiency of the ApoC2 gene exhibit hypertriglyceridemia." (PMID 39798876, 2025). "APOC2-related hypertriglyceridemia occurs due to biallelic variants of this gene." (PMID 38938447, 2024). "Familial hypertriglyceridemia is the result of a single gene mutation, usually in the lipoprotein lipase (LPL) or ApoC2 or ApoA5 genes involved in TG metabolism, and manifests as severe hypertriglyceridemia (TG > 10 mmol/L) with an incidence of about 1 in 1 million." (PMID 37711173, 2023). "APOC2 deficiency can cause severe hypertriglyceridemia and lead to cardiovascular disease." (PMID 36072434, 2022). "APOC2 mutations could cause hyperlipoproteinemia type IB, characterized by hypertriglyceridemia, xanthomas, and early atherosclerosis." (PMID 33828156, 2021). "A deficiency in the apolipoprotein C2 (APOC2) can be causative of hypertriglyceridemia." (PMID 32971894, 2020). "Similarly, ApoC2 functions as cofactor in LPL-mediated TG hydrolysis and ApoC2 deficiency in humans is associated with severe hypertriglyceridemia." (PMID 23469003, 2013). "It has been demonstrated that Apoc2−/− mice develop metabolic defects including hypertriglyceridemia and acute recurrent pancreatitis." (PMID 39798876, 2025).
hypertriglyceridemia (continued). "This study utilized apolipoprotein C2 (Apoc2) knockout golden Syrian hamster models with hypertriglyceridemia." (PMID 39811454, 2024). "Decreasing plasma triglycerides (TGs) by activating lipoprotein lipase (LPL) with ApoC2 mimetic peptides is a new treatment strategy for hypertriglyceridemia." (PMID 37547254, 2023). "Finally, we considered the fact that ApoC2 is a critical activator of LPL activity as shown by the fact that ApoC2 deficiency results in severe hypertriglyceridemia and wondered what the effects of ANGPTL4/8-mediated plasmin generation might be on ApoC2-mediated stimulation of LPL activity." (PMID 37666362, 2023). "ApoC2 is well known to be a critical LPL activator required for TG hydrolysis, as evidenced by the fact that ApoC2 deficiency causes severe hypertriglyceridemia." (PMID 37666362, 2023). "Most variants interfering with triglyceride metabolism and causing hypertriglyceridemia are loss of function variants (LOF), and mainly found in the LPL, APOC2, APOA5, LMF1 and GPIHBP1 genes." (PMID 35237305, 2022). "Our NGS analysis revealed 10 rare variants at 4 genes (APOA1, APOA4, APOC2, and LMF1) related to hypertriglyceridemia." (PMID 35999587, 2022). "The most severe type of HTG is primary (or hereditary) hypertriglyceridemia, linked to pathogenic genetic variants in LPL, APOC2, LMF1, and APOA5 genes." (PMID 35741823, 2022). "For severe hypertriglyceridemia, pathogenic variants in genes LPL, APOA5, APOC2, GPIHBP1, and LMF1, associated with hyperlipidemia should be considered." (PMID 36051701, 2022). "A mutation on exon 3 of the APOC2 (c.86A > CC) can significantly decrease LPL activity in plasma and significantly increase triglyceride levels in serum, resulting in severe hypertriglyceridemia." (PMID 36011378, 2022). "A set of 53 single nucleotide polymorphisms (SNPs) previously associated with triglycerides levels, as well as 37 rare variants within the five main genes associated with hypertriglyceridemia (i.e. LPL, APOC2, APOA5, LMF1 and GPIHBP1) were analyzed." (PMID 33588820, 2021). "Variants on genes known to cause severe hypertriglyceridemia such as LPL, APOC2, GPIHBP1, APOA5, and LMF1 were first selected and interpreted." (PMID 32765589, 2020). "The hypertriglyceridemia was then rescued by injection of plasma from wildtype zebrafish with functional APOC2 or by injection of a human APOC2 mimetic peptide." (PMID 32849290, 2020). "In contrast, APOC2 is a cofactor of LPL and its loss of function results in deficient LPL activity and consequent hypertriglyceridemia and chylomicronemia." (PMID 26044956, 2015). "Severe hypertriglyceridemia (HTG) has been linked to defects in LPL, APOC2, APOA5, LMF1 and GBIHBP1 genes." (PMID 23151256, 2012). "Mutations in genes encoding lipoprotein lipase, apolipoprotein C-II (APOC2), apolipoprotein A-V (APOA5), and other enzymes involved in lipid metabolism have been associated with severe hypertriglyceridemia, particularly when triggered by medications or metabolic stress." (PMID 40862038, 2025). "Although the mechanisms causing hypertriglyceridemia are not fully understood, certain genetic mutations, such as Apolipoprotein E mutations, APOA5 mutation, and APOC2 mutation, may be involved, leading to protein defects and function loss." (PMID 39267857, 2024). "Severe hypertriglyceridemia, in the form of Familial Chylomicronaemia Syndrome (FCS), is a rare autosomal recessive disease caused by pathogenic variants especially in the LPL gene but also in APOC2, APOA5, LMF1 and GPIHBP1." (PMID 35237305, 2022). "Besides LPL, there are other genes involved in primary hypertriglyceridemia phenotypes (most notably, APOC2, APOA5, LMF1, and GPIHBP1)." (PMID 36051701, 2022).
hypertriglyceridemia (continued). "Novel homozygous apolipoprotein C2 (APOC2)-ablated golden Syrian hamster that exhibits severe hypertriglyceridemia was established with CRISPR/Cas9, and the genetically modified hamster is useful to study the APOC2 function and its effect on lipid and glucose homeostasis." (PMID 34445123, 2021). "Alteration in APOC2 was involved in progression of hypertriglyceridaemia, but this gene may be responsible for the development of CAD." (PMID 31881747, 2019). "Variants in the lipoprotein lipase (LPL), apolipoprotein C-II (APOC2), apolipoprotein A-V (APOA5), GPIHBP1 and LMF1 genes may cause severe hypertriglyceridemia (HTG), which is now the second-leading aetiology of acute pancreatitis in China." (PMID 29921298, 2018). "LncRNA, liver-specific triglyceride regulator, was recently identified and showed to inhibit apolipoprotein C2 (apoC2) expression through a famesoid X receptor-mediated pathway, whose depletion led to robust lipoprotein lipase activation and hypertriglyceridemia." (PMID 28275212, 2017). "The familial chylomicronemia syndrome (FCS) patients, who have deficiency in APOC2 or LPL, consuming normal diet develop severe hypertriglyceridemia and chylomicronemia and often manifest eruptive xanthomas, lipemia retinalis, and acute and recurrent pancreatitis." (PMID 28107429, 2017). "Loss-of-function mutations in APOC2 and LPL are associated with severe hypertriglyceridemia." (PMID 19878569, 2009). "Genetic deletion of ApoC2 impairs the ability of LPL to break down lipoproteins that are rich in triglycerides, resulting in a significant increase in plasma triglyceride levels and eventually causing severe hypertriglyceridemia and spontaneous atherosclerosis." (PMID 39798876, 2025). "Similarly, there is a familial hypertriglyceridaemia in humans, characterized by an increase in the production of VLDL and apolipoprotein C-II (APOC2) deficiency, in humans is a very rare cause of hyperkylomycinemia, the most common cause is deficiency of lipoprotein lipase (LPL)." (PMID 34665804, 2021). "Multiple regression analysis indicated that low LPL, high ApoC2, high ApoC3, high ApoE, and high ANGPTL8 levels were the determinants of fasting hypertriglyceridemia." (PMID 34293055, 2021). "However, because APOC2 does not have a catalytic activity and LPL is not functional without APOC2, both mutants developed hypertriglyceridemia." (PMID 29615667, 2018). "Animal models to study hypertriglyceridemia are limited, with no Apoc2-knockout mouse reported." (PMID 26044956, 2015). "In 2012, we found an excessive prevalence of rare variants in LPL, APOC2, GPIHBP1, APOA5, and LMF1 in patients with severe hypertriglyceridemia, again indicating that heterozygosity was a predisposing factor for, although not an absolute cause of severe hypertriglyceridemia or MCM." (PMID 32793115, 2020).
atherosclerosis (12 papers, 2012 to 2025). A disease characterized by the build-up of fatty material and calcium deposition in the arterial wall resulting in partial or complete occlusion of the arterial lumen. "It is important to note that ApoC2 has already been linked to HDL and atherosclerosis." (PMID 22761902, 2012).
dyslipidemia (12 papers, 2014 to 2025). "Additionally, elevated levels of APOH, APOC2, and APOC3 have been linked to clinically apparent arteriosclerosis and components of metabolic syndrome (MetS)." (PMID 38034020, 2023).
familial chylomicronemia syndrome (12 papers, 2016 to 2024). A rare autosomal recessive disease characterized by the buildup in the blood of fat particles called chylomicrons (chylomicronemia), severe hypertriglyceridemia, and the risk of recurrent and potentially fatal pancreatitis and other complications. "(B) Familial chylomicronemia syndrome (FCS) is a syndrome characterized by high levels of chylomicrons due to autosomal recessive mutation of the lipoprotein lipase (LPL) gene located on chromosome 8p21.3 or the Apolipoprotein C2 (APOC2) gene located on chromosome 19q13.32." (PMID 36012138, 2022). "APOC2 is the obligate activator of LPL, and APOC2 deficiency leads to familial chylomicronemia syndrome." (PMID 34981790, 2022). "At the genetic level, severely elevated triglyceride levels resulting from familial chylomicronemia syndrome (FCS) are caused by homozygous or biallelic loss-of-function variants in LPL, APOC2, APOA5, LMF1, and GPIHBP1 genes." (PMID 32793115, 2020). "When due to very rare monogenic mutations in the genes encoding the enzyme, lipoprotein lipase, or its regulators, APOC2, APOA5, GPIHBP1, and LMF1, it is referred to as the familial chylomicronemia syndrome." (PMID 33193106, 2020). "Familial chylomicronemia syndrome (FCS) is a rare disorder of triglyceride (TG) metabolism caused by loss of function variants in one of five known canonical genes involved in chylomicron lipolysis and clearance—LPL, APOC2, APOA5, LMF1, and GPIHBP1." (PMID 38974610, 2024).
hyperlipidemia (12 papers, 2014 to 2024). "Current genetic animal models to study hyperlipidemia include mice with a conditional deficiency in LPL, deficiency of GPIHBP1, or with overexpression of human APOC2 and APOC3." (PMID 26044956, 2015). "Two patients with other five family members were included in this study for DNA-sequences of hyperlipidemia-related genes (such as LPL, APOC2, APOA5, LMF1, and GPIHBP1) and 43 healthy individuals and 70 HTG subjects were included for the screening of LPL gene mutations." (PMID 24646025, 2014). "We speculated that compared with the severe combined hyperlipidemia in ApoC2-/- hamsters, the relatively lower lipid levels were not sufficient to initiate the visible atherosclerotic lesions in ApoA5-/- hamsters." (PMID 38505614, 2024).
Obesity (11 papers, 2017 to 2025). Accumulation of substantial excess body fat. "Hub genes of GAL, APOE, APOC2, and NPPB have been demonstrated to be associated with obesity as follows: (I) GAL: Galanin peptides, as the protein for GAL, is undoubtedly involved in the regulation of food intake and body weight." (PMID 29132311, 2017). "Interestingly, chronic CS exposure also enhanced Fapb1 and Apoc2 expression in the gut of lean mice and had additive effect on obesity-induced Fabp1 and Apoc2 expression." (PMID 32244932, 2020).
pancreatitis (10 papers, 2012 to 2025). Inflammation of the pancreas. "Biallelic pathogenic variants in LPL or APOC2 accounted for <5% of all cases but were associated with the most extreme phenotypes (mean TG > 2800 mg/dL) and the highest burden of pancreatitis (>70% with ≥1 prior episode)." (PMID 41300829, 2025). "Current treatment options for severely hypertriglyceridemic patients with loss-of-function mutations in APOC2 include a stringent low-fat diet and plasma exchange with APOC2-containing donor plasma as a direct and lifesaving procedure during severe pancreatitis episodes." (PMID 32849290, 2020). "FCS due to biallelic LPL, APOC2, GPIHBP1, or LMF1 variants accounted for <5% of cases and showed extreme TG elevations (>2800 mg/dL) with pancreatitis prevalence (>70%)." (PMID 41300829, 2025).
type 2 diabetes (8 papers, 2012 to 2023). "Although APOC2 is a critical factor for LPL activity and APOA5 stabilized LPL‐APOC2 complex, the reports of circulating levels of APOC2 and APOA5 as biomarkers in patients with type 2 diabetes are scarce." (PMID 37448184, 2023). "In type 2 diabetes patients with or without diabetic retinopathy, multivariate logistic regression analysis showed that APOC2/APOC3 and APOB/non‐HDL cholesterol, as well as APOE/APOC2, were independently related to the risk for the occurrence and severity of diabetic retinopathy." (PMID 37448184, 2023).
breast carcinoma (7 papers, 2019 to 2025). "Analysis of data from the TCGA database revealed that APOC2 is significantly upregulated in multiple tumor types, including clear cell renal cell carcinoma (ccRCC), bladder urothelial carcinoma, colorectal cancer, breast cancer, and esophageal carcinoma." (PMID 41296440, 2025). "The patients exhibited significantly lower levels of key apolipoproteins, including apoA-1, apoA-2, apoC-2, and apoC-4, compared to luminal A, luminal B, and HER2-positive breast cancer patients (p-values ranging from 0.004 to 0.057)." (PMID 40430118, 2025). "In pancreatic cancer, APOA2, APOC1, APOC2, and APOJ have been described, while APOB was found in HCC, bladder, and breast cancer." (PMID 37628784, 2023).